PFDN5 (prefoldin subunit 5)
Description:
Binds specifically to cytosolic chaperonin (c-CPN) and transfers target proteins to it. Binds to nascent polypeptide chain and promotes folding in an environment in which there are many competing pathways for nonnative proteins. Represses the transcriptional activity of MYC.
Synonyms: MM1; PFD5; MM-1
Tractability: Small molecule: a structure with a bound ligand is known. PROTAC: ubiquitination databases record sites on it; its protein half-life has been measured.
Gene: Protein-coding gene on chromosome 12 (53,295,291 to 53,299,452, forward strand). Ensembl gene ENSG00000123349.
Subcellular location: Nucleus (Isoform 1); Cytoplasm (Isoform 2); Nucleus (Isoform 3)
Subcellular location (Human Protein Atlas): Cytosol; Intermediate filaments
Pathways (Reactome):
Metabolism of proteins: Prefoldin mediated transfer of substrate to CCT/TriC
Gene Ontology:
Molecular function: amyloid-beta binding; protein binding; transcription corepressor activity
Biological process: negative regulation of amyloid fibril formation; negative regulation of canonical Wnt signaling pathway; negative regulation of DNA-templated transcription; protein folding; protein stabilization; regulation of DNA-templated transcription; RNA polymerase I assembly; RNA polymerase II core complex assembly; RNA polymerase III assembly
Cellular component: cytosol; prefoldin complex; cytoplasm; nucleus; protein folding chaperone complex
Genetic constraint (gnomAD): Loss-of-function variants: 6 observed, 6.22 expected, observed/expected ratio (o/e) 0.96, 90% interval 0.52 to 1.75. That is too few expected variants to judge how well the gene tolerates losing a copy. Missense variants: 64 observed, 54.66 expected, observed/expected ratio (o/e) 1.17, 90% interval 0.96 to 1.44. Synonymous variants: 35 observed, 25.83 expected, observed/expected ratio (o/e) 1.35, 90% interval 1.03 to 1.77.
Homologues: Orthologues: chimpanzee PFDN5 (100% identical), macaque PFDN5 (100% identical), guinea pig PFDN5 (99% identical), mouse Pfdn5 (99% identical), pig PFDN5 (99% identical), rabbit PFDN5 (99% identical), rat Pfdn5 (99% identical), zebrafish pfdn5 (78% identical), Drosophila melanogaster Pfdn5 (37% identical), Caenorhabditis elegans pfd-5 (31% identical).
Diseases named in the same sentence as PFDN5 in open-access papers:
PFDN5 is named in the same sentence as 36 diseases in open-access papers, as found by Europe PMC text mining. Sharing a sentence is not in itself a finding about the gene and the disease. The quoted sentences say what the papers report.
breast cancer (7 papers, 2013 to 2024). A primary or metastatic malignant neoplasm involving the breast. "Decreased levels of PFDN5 is observed in breast carcinoma specimens, indicating its potential role as a diagnostic or prognostic marker." (PMID 39495117, 2024). "Somatic deletion of the PFDN5 gene has been observed in canine mammary cancer, particularly in solid tumors, correlating with a high Ki-67 score (tumor proliferation marker)." (PMID 38216914, 2024). "A somatic deletion of the PFDN5 gene is recurrently present in canine mammary cancer, supporting a potential role in carcinogenesis." (PMID 26132936, 2015). "In human breast cancer PFDN5 was amongst 102 genes for which differential expression in tumor versus normal tissue was detected; 69% of the analysed tumor samples showed a decreased expression." (PMID 26132936, 2015). "The present study confirms and extends our previous findings of the abundance of a deletion of the proximal part of CFA27 harbouring the PFDN5 gene in canine mammary tumors." (PMID 26132936, 2015). "PFDN5 gene somatic cell deletion is more common in canine breast cancer and it is common and closely related to high Ki-67 scores, indicating that down-regulation or deletion of PFDN5 expression has a very important role in the development of canine breast cancer." (PMID 32699605, 2020). "Future studies are needed to determined whether the recurrent PFDN5 deletion can be confirmed in a larger group and whether this deletion is specific to mammary tumors." (PMID 24098698, 2013). "In breast cancer datasets, the five most important mRNAs were GABARAP, PFDN5, RPL21, CFB, and PCED1A." (PMID 39495117, 2024). "PFDN5 has been described to repress c-MYC and is, therefore, a candidate tumor-suppressor and cancer-driver gene in canine mammary cancer." (PMID 26132936, 2015). "Additionally, TiHo-0906 cells at low and high passage also displayed CNGs in regions harbouring other known breast cancer-related genes like FOXO3 and MYB (FCA B2), AKT1 (FCA B3), and GATA-3, CCND2, CDK4 and PFDN5 (FCA B4)." (PMID 30185896, 2018). "Due to the location of PFDN5 close to the centromere it can not be excluded that its frequent deletion in canine mammary tumors is solely related to its position." (PMID 26132936, 2015).
uveitis (6 papers, 2020 to 2023). An inflammatory process affecting a part of or the entire uvea. "Among autoantibodies, IgG against the intracellular protein prefoldin subunit 5 (PFDN5), which is a protein with a protective role in the apoptosis of retinal cells, are recently observed in AS patients, especially in those with uveitis." (PMID 36308677, 2023). "Reactivity against prefoldin subunit 5 (PFDN5) was identified in AS with uveitis, which was validated in mice model and apoptosis assay." (PMID 34012435, 2021). "PFDN5 also revealed a protective role against apoptosis of retinal cells, preventing cell death in uveitis." (PMID 33343583, 2020). "The functional meaning of these anti-PFDN5 antibodies is not clear yet, and the potential value of these antibodies as a biomarker for risk of uveitis in AS patients warrants further investigation." (PMID 34948121, 2021). "In uveitis, PFDN5 upregulation might be involved in protecting retinal cells against cell death." (PMID 35111762, 2021). "Significantly elevated levels of PFDN5 antibodies and free PFDN5 were found in AS patients with uveitis compared to AS patients without this manifestation and non-AS patients." (PMID 34948121, 2021). "A significantly higher level of anti-prefoldin subunit 5 (PFDN5) antibodies were found in sera of AS patients with uveitis, as compared to AS without uveitis." (PMID 33343583, 2020). "Compared with AS patients without uveitis, AS patients with uveitis had significantly higher serum PFDN5 levels, and PFDN5 had a protective effect on uveitis cell death, suggesting that PFDN5 can be used as a biomarker for AS uveitis." (PMID 32699605, 2020).
Hypercholesterolemia (2 papers, 2013 to 2020). An increased concentration of cholesterol in the blood. "Therefore, the study of the PFDN5 gene may help to clarify the mechanism of the link between hypercholesterolemia and cognitive deficits." (PMID 32699605, 2020). "Among the DEGs that were down-regulated in the hypercholesterolemia plus sham group vs. sham controls were beta tropomyosin (LOC100125984), PFDN5 and CUL3." (PMID 23874591, 2013). "Studies have shown that PFDN5 may be an important component of synaptic plasticity in the hippocampus of mice and exposed to hypercholesterolemia in New Zealand white rabbits’ prefrontal cortex (PFC), PFDN5 is one of the genes whose expression is down-regulated." (PMID 32699605, 2020).
Alzheimer disease (1 paper, 2026). A progressive, neurodegenerative disease characterized by loss of function and death of nerve cells in several areas of the brain leading to loss of cognitive function such as memory and language. "In addition, several lines of supportive evidence from human Alzheimer’s disease datasets implicate PFDN5 in disease pathology." (PMID 41533771, 2026).
bladder cancer (1 paper, 2023). "CDK4, KPNA2, PFDN5, HSP90B1, and ZNF121 were identified as prognostic differential genes in bladder cancer." (PMID 37433010, 2023).
cardiomyopathy (1 paper, 2025). A disease of the heart muscle or myocardium proper. "We observed dysregulated alternative splicing of PFDN5 and RPS24 is associated with the development of cardiomyopathy.Splicing defects in PFDN5 impair cytoskeletal protein folding, while RPS24 dysregulation affects their translation, disrupting actin and tubulin homeostasis." (PMID 40382596, 2025). "We identified alternative transcripts of RPS24 and PFDN5 genes among childhood cancer survivors with anthracycline-induced cardiomyopathy." (PMID 40382596, 2025). "RPS24 transcript ENST00000372360 and PFDN5 transcript ENST00000551018 had higher expression in patients with cardiomyopathy with direct correlation of intron retention and exon skipping to lower transcript level expression in controls." (PMID 40382596, 2025). "Splicing alterations resulting in differential expression of splicing isoforms in RPS24 and PFDN5 could compromise protein homeostasis, cardiac structure, and stress response, ultimately contributing to cardiomyopathy (Central Illustration)." (PMID 40382596, 2025).
Cognitive impairment (1 paper, 2026). Abnormal cognition is characterized by deficits in thinking, reasoning, or remembering. "Since the overexpression of Pfdn5 restored the Tau-induced neurological abnormalities to the control levels without causing any detectable changes in synaptic morphology, cognitive impairment, or organismal health, we suggest that Pfdn5 could be a possible therapeutic target for Tauopathies." (PMID 41533771, 2026).
heart failure (1 paper, 2025). Inability of the heart to pump blood at an adequate rate to meet tissue metabolic requirements. "Splicing alterations in PFDN5 may impair the proper folding of actin and tubulin, leading to cytoskeletal abnormalities that contribute to heart failure and arrhythmias." (PMID 40382596, 2025).
hypertrophic cardiomyopathy (1 paper, 2025). A condition in which the myocardium is hypertrophied without an obvious cause. "al., identified RPS24 and PFDN5 as key hub genes that are dysregulated in hypertrophic cardiomyopathy samples compared to healthy controls." (PMID 40382596, 2025).
ischemic stroke (1 paper, 2022). A stroke disorder caused by obstruction of blood flow to the brain, due to thrombotic (local blood clot formation) or embolic (due to a blood clot or other material traveling from another site) event. "Our findings suggest a close association of PABPC1, PFDN5, and TNF with female ischemic stroke patients." (PMID 35432523, 2022).
leukaemia (1 paper, 2014). "A point mutation in PFDN5, which is often observed in patients with leukaemia or lymphoma, abrogates all of its repressive activities towards c-Myc, indicating that PFDN5 behaves like a tumour suppressor." (PMID 25008233, 2014).
lymph node metastasis (1 paper, 2024). "KDM5C expression was found to be positively correlated with lymph node metastasis and advanced tumor node metastasis (TNM) staging, while PFDN5 expression correlated negatively with both." (PMID 38216914, 2024).
male infertility (1 paper, 2020). The inability of the male to effect fertilization of an ovum after a specified period of unprotected intercourse. "L110R mice with PFDN5 missense mutations have defective spermatogenesis and reduced expression of sperm-related genes, which are manifested as male infertility." (PMID 32699605, 2020).
Obesity (1 paper, 2025). Accumulation of substantial excess body fat. "In the obesity signature, eight genes were found to possess regulatory functions: COPS5, GATA2, MORF4L1, OPTN, PFDN5, SETBP1, TCF4, and ZBTB16." (PMID 40102990, 2025).
retinal degeneration (1 paper, 2019). Degeneration of the retina. "Importantly, genetic disruption of PFDN5 in mice causes retinal degeneration." (PMID 30891043, 2019).
secondary hyperparathyroidism (1 paper, 2020). Overproduction of parathyroid hormone in response to influence external to the parathyroid glands. "PFDN5 is differentially expressed in thyroid tumor tissue, and abnormal expression of PFDN5 that associated with protein synthesis and processing has been detected in secondary hyperparathyroidism." (PMID 32699605, 2020).
spondylitis (1 paper, 2019). The inflammation of a vertebra. "To assess the possibility of PFDN5 and anti-PFDN5 as a biomarker of disease activity in AS, we also analyzed the correlation of PFDN5 and anti-PFDN5 antibody with Bath Ankylosing Spondylitis Disease Activity Index (BASDAI) in the Korean cohort (data not shown in the Results)." (PMID 30891043, 2019).
Tauopathies (1 paper, 2026). "To determine if loss of Pfdn5 specifically modulates FTDP-17-associated Tau mutations or also influences sporadic Tauopathy linked to wild-type Tau, we expressed hTauWT in Pfdn5 mutants." (PMID 41533771, 2026). "The observations above indicate that loss of Pfdn5 enhances the neurotoxicity in the Drosophila Tauopathy model." (PMID 41533771, 2026). "Our findings that loss of Pfdn5 disrupts microtubules at an early stage and leads to Tau aggregation further support the crucial requirement of Pfdn5-dependent microtubule stability in suppressing various forms of Tauopathy." (PMID 41533771, 2026). "Altogether, these data indicate that increased expression of Pfdn5 or Pfdn6 can remarkably counteract neuronal loss and delay the onset and progression of the neurodegenerative cascade induced in Tauopathy through a mechanism that involves Pfdn-mediated microtubule stabilization." (PMID 41533771, 2026). "However, coexpression of Pfdn5 or Pfdn6 with the pathological variant of hTau remarkably suppressed Tau-induced synaptic defects, prevented brain vacuolization, and rescued memory defects in multiple forms of tauopathies." (PMID 41533771, 2026). "Moreover, neuronal expression of Pfdn5 and TauWT or TauV337M rescues the synaptic defects, suggesting that Pfdn5 can alleviate multiple forms of Tauopathy." (PMID 41533771, 2026).
tumor (12 papers, 2013 to 2024). "Further indication for the proposed role of PFDN5 as tumor-suppressor is the detected association between CFA27 deletion and higher Ki-67 scores." (PMID 26132936, 2015). "PFDN5, also known as Myc-modulator 1, is reported as a binding protein of the protooncogene c-Myc, influencing its transcriptional activity and theoretically playing a tumor-suppressive function." (PMID 38216914, 2024). "Our pertinent findings indicate that patients with PFDN5 overexpression in the tumor tissue had higher mortality rates, and those having PFDN1 overexpression also showed higher rates of recurrence, specifically for distant metastasis." (PMID 32344577, 2020). "Due to the low content of malignant cells in the so called carcinomas in benign tumors (n = 21), the KI-67 was reduced, congruent with the low abundance of the PFDN5 deletion in the whole tissue of that tumor type." (PMID 26132936, 2015). "PFDN5 - also termed cMYC modulator MM1– is described as a tumor suppressor that acts by repressing the expression of the cMYC oncogene product." (PMID 24098698, 2013). "Only the prefoldin subunit 5 gene (PFDN5) has previously been described as a tumor suppressor gene and, therefore, is the most conclusive candidate for possible functional impact." (PMID 24098698, 2013). "Similarly, the tumor weight was significantly reduced when KDM5C was silenced but enhanced when PFDN5 was further knocked down." (PMID 38216914, 2024). "Additionally, the IHC assay revealed that the intensity of cleaved-caspase-3 staining, a marker of apoptosis, in tumor tissues was enhanced after KDM5C silencing but weakened upon PFDN5 downregulation." (PMID 38216914, 2024). "The results of a cDNA microarray analysis of clinical colorectal cancer samples suggested that PFDN5 may be a useful tumor histology and prognosis marker." (PMID 35111762, 2021). "PFDN5 has been suggested to have a tumor-suppressing function." (PMID 35111762, 2021). "Furthermore, the somatic presence of the deletion in 23% of the analysed malignant tumors supports PFDN5 as being a potential tumor driver gene." (PMID 26132936, 2015). "PFDN5, a known negative regulator of c-Myc and thus a potential tumor suppressor, exhibiting a remarkable negative correlation with KDM5C expression, ranking second in correlation coefficient, was consequently chosen for subsequent analysis." (PMID 38216914, 2024). "For instance, In tumor-immune interface-3, pro-tumor expression markers are TIMP1, a member of MMPs involved in the degradation of the extracellular matrix, whereas IGFBP4, PFDN5, CD63 repress tumor progression." (PMID 35835774, 2022).
cancer (7 papers, 2013 to 2025). A tumor composed of atypical neoplastic, often pleomorphic cells that invade other tissues. "Screening for cancer-associated genes in this region revealed PFDN5 as most probably affected by the recurrent deletion." (PMID 24098698, 2013). "Only two cancer associated genes PFDN5 and TMBIM6 were found in the deleted region." (PMID 24098698, 2013). "Despite the generally low PSI values for the 325 cryptic 3’SSs from the CLL-only analysis, we identified four genes previously implicated in cancer (TTI1, MAP3K7, FXYD5, PFDN5) and six others (YIF1A, ORAI2, ZNF91, ZNF548, RP11–1280I22." (PMID 25768983, 2015). "Within this region PFDN5 appeared as the most plausible candidate with cancer-driving functional relevance." (PMID 26132936, 2015). "The confirmation of earlier results warrants further studies on PFDN5 as cancer-driver gene." (PMID 26132936, 2015). "However, little is known about the precise role of PFDN5 in cancer progression." (PMID 38216914, 2024). "Considering the reported association between c-Myc signal transduction and autophagy inhibition during cancer progression, we hypothesized that KDM5C/PFDN5 might influence the autophagy activity of CRC cells." (PMID 38216914, 2024). "The Ki-67 score was found to be significantly higher (p<0.05) in the PFDN5-deleted group compared to malignant tumors without the deletion." (PMID 26132936, 2015). "However, PFDN5 cannot be considered as a well-known established cancer-driver gene, neither in human nor in canine cancers." (PMID 26132936, 2015).
kidney diseases (1 paper, 2024). "This suggests that TUBB6 may be used as a potential biomarker to compare two related kidney diseases (FSGS and MCD), and TUBB6, RPL27, and PFDN5 can be used as potential biomarkers to detect FSGS." (PMID 39519211, 2024).
PFDN5 also shares sentences with these, for which no sentence is quoted: ankylosing spondylitis (1 paper); benign tumors (1); Cerebellar atrophy (1); childhood cancer (1); chronic heart failure (1); colorectal cancer (1); focal segmental glomerulosclerosis (1); gastric cancer (1); glomerulosclerosis (1); infection (1); lymphoma (1); memory impairment (1); neurodegenerative disease (1); non-small cell lung carcinoma (1); thyroid tumor (1).